IGKV1D-32 (immunoglobulin kappa variable 1D-32 (pseudogene))
Synonyms: IGKV1D32; O9
Gene: Immunoglobulin variable (V) pseudogene on chromosome 2 (89,928,422 to 89,928,867, forward strand). Ensembl gene ENSG00000253191.
Diseases named in the same sentence as IGKV1D-32 in open-access papers:
IGKV1D-32 is named in the same sentence as 2 diseases in open-access papers, as found by Europe PMC text mining. Sharing a sentence is not in itself a finding about the gene and the disease.
IGKV1D-32 shares sentences with these, for which no sentence is quoted: infection (4 papers); Salmonella Infections (1).